GPC3 (glypican 3)
Diseases named in the same sentence as GPC3 in open-access papers (continued):
Sharing a sentence is not in itself a finding about the gene and the disease.
Wilms tumor (20 papers, 2002 to 2025). An embryonal neoplasm characterized by the presence of epithelial, mesenchymal, and blastema components. "A study of the GPC3 promoter methylation in primary pediatric embryonal tumors revealed gain of methylation mainly in boys with Wilms tumor and loss of methylation exclusively in girls with neuroblastoma." (PMID 30873384, 2019). "Tumour and normal tissue from 41 male cases of Wilms' tumour were screened to determine the presence of sequence variants in the glypican 3 (GPC3) gene." (PMID 12085187, 2002). "In addition to constitutional mutations seen in patients with SGBS, somatic tumor mutations in GPC3 have even been identified in some cases of Wilms tumors." (PMID 30873384, 2019). "In addition, the nephroblastoma-related glycoprotein glypican-3 (GPC3) may serve as a diagnostic marker, especially when its expression in certain tumor types is considered." (PMID 40142302, 2025). "Elevated transcriptional and proteomic expression of GPC3 is evident in a significant portion of Wilms tumors, as compared with adult kidney tumors and normal kidney tissue." (PMID 30873384, 2019). "A loss of function mutation of glypican-3 is associated with Simpson-Golabi-Behmel (SGB) syndrome, which has pre and postnatal overgrowth and risk of embryonic tumors such as Wilms tumors and neuroblastomas, the latter a tumor of neuronal origin." (PMID 18088439, 2007). "We have previously shown that the glypican 3 (GPC3) gene was expressed in neuroblastoma (NB) and Wilms' tumour (WT), two embryonal tumours." (PMID 15083193, 2004). "Glypican 3 (GPC3) gene has been shown to be expressed in neuroblastoma (NB) and Wilms' tumour (WT), two embryonal tumours." (PMID 15083193, 2004). "The GPC3 variant was backed by moderate (“PM5”) computational and predictive data as it modifies the same amino acid residue as another pathogenic missense variant in ClinVar associated with Wilms tumor." (PMID 37461096, 2023). "This represents the first fully documented report of such mutations in tumour tissue and provides evidence that disruption of the GPC3 protein may be involved in initiation, development or progression in some Wilms' tumours." (PMID 12085187, 2002).
liver cirrhosis (19 papers, 2014 to 2023). "Compared to individuals with liver cirrhosis caused by HCV infection, GPC3 serum levels are higher in HCC patients." (PMID 37509493, 2023). "GPC3 expression was observed in the livers with liver cirrhosis (LC; 16.8%, 32/191) and DN (50.0%, 4/8)." (PMID 33824478, 2021). "We investigated serum alpha-fetoprotein (AFP), protein induced by vitamin K absence or antagonist II (PIVKA-II) and glypican-3 (GPC-3) diagnostic accuracy for HCC detection and prediction in patients with liver cirrhosis of viral etiology under surveillance." (PMID 33142893, 2020). "ROC curves were performed to determine the diagnostic values and optimum cutoff of GPC3, miR-122 and AFP for early-stage HCC from all controls (LC+CH+HC, patients of liver cirrhosis and chronic hepatitis C carriers and health controls)." (PMID 33817137, 2019). "High GPC-3 expression (P < 0.001), liver cirrhosis (P = 0.008) and HBV infection (P = 0.006) were all identified as independent predictive factors for worse HCC outcome." (PMID 27286460, 2016). "But four studies have found lowered or equivalent serum levels of GPC3 in HCC patients compared with liver cirrhosis patients." (PMID 25378766, 2014). "In fact, all four studies observed that serum GPC3 level is higher in liver cirrhosis patients than that in HCC patients." (PMID 25378766, 2014). "Of course, additional studies must be performed to investigate the potential role of GPC3 during liver cirrhosis transformation to HCC." (PMID 24498024, 2014). "GPC3 can distinguish eHCC-G1 from the dysplastic nodules of liver cirrhosis, indicating that GPC3 could be used as a biomarker for the early detection of HCC." (PMID 35331259, 2022). "An elevated GPC3 level is revealed in 50–55% of HCC patients and only in 5% of those with liver cirrhosis." (PMID 34513063, 2021). "In the HBV-HCC and HCV-HCC subgroups, the levels of AFU, GPC3, and GGT-II were significantly higher in the LC group than in the CH group, suggesting that elevated levels of these three biomarkers may be associated with the progression of hepatitis to liver cirrhosis." (PMID 33628599, 2021). "Moreover, a rapid increase in GPC-3 expression is also linked to the progression of precancerous lesions to HCC Moreover, GPC-3 detection allows HCC to be distinguished from healthy liver tissue, benign lesions, and liver cirrhosis." (PMID 36901717, 2023). "None of the multiple biomarkers included in the analyses (age, tumor number, intratumoral lymphocytes, liver cirrhosis, Hep Par 1, CD34, Glypican 3) reached statistical significance (p = 0.68, p = 0.22, p = 0.54, p = 0.60, p = 0.68, p = 0.79, and p = 0.53, respectively)." (PMID 37174934, 2023). "We found that elevated GPC3 level is not unique for HCC but is also found in liver cirrhosis patients." (PMID 25378766, 2014). "Simultaneously, the occurrence of small focal positivity for GPC3 in liver cirrhosis indicated strongly HCC regardless of the percentage of positive cells for GPC3." (PMID 24498024, 2014). "This meta-analysis indicates that serum GPC3 is elevated in HCC patients compared with healthy individuals, but more studies are needed to evaluate its effectiveness to differentially diagnose HCC and liver cirrhosis." (PMID 25378766, 2014). "However, GPC3 could be more specific for HCC than ARG1, which will be important for differentiating HCC from liver cirrhosis." (PMID 35331259, 2022). "Of these, eight proteins, glypican 3 (GPC3), squamous cell carcinoma antigen (SCCA), haptoglobin, C3 precursor, seprase, hemoglobin subunit gamma, hemoglobin subunit alpha, and teneurin-3, showed higher relative peaks in HCC cases with normal AFP levels than the liver cirrhosis controls." (PMID 31979338, 2020). "But whether GPC3 is an index to differentially diagnose HCC and liver cirrhosis is still uncertain." (PMID 25378766, 2014).
liver cirrhosis (continued). "Lots of tissue microarray and immunohistochemical data showed that GPC3 is highly expressed in more than 70% of HCC samples, but not in normal liver tissues, benign liver lesions, liver cirrhosis or hepatitis tissues 5, 63-65." (PMID 32127929, 2020). "Therefore, elevated serum GPC3 level is not a unique feature in HCC and is also seen in liver cirrhosis patients." (PMID 25378766, 2014). "Serum glypican-3 (GPC-3) is an oncofetal protein which is normally not expressed in adult liver; several studies showed a good performance of GPC-3 for the discrimination between patients with HCC and liver cirrhosis, however, data on Caucasian patients are scanty." (PMID 33142893, 2020).
cholangiocarcinoma (18 papers, 2012 to 2026). A carcinoma that arises from the intrahepatic biliary tree (intrahepatic cholangiocarcinoma) or from the junction, or adjacent to the junction, of the right and left hepatic ducts (hilar cholangiocarcinoma). "Third, due to the low expression of Arg-1 and GPC-3 in cholangiocarcinoma tissues, the sample size was small." (PMID 34715880, 2021). "For instance, Arg-1 demonstrates superior sensitivity (85.7%) in poorly differentiated HCC compared to HepPar1 (46.4%), but its occasional reactivity in cholangiocarcinoma (6.9%) necessitates integration with GPC3 (specificity 97.3%) or pCEA (canalicular pattern specificity)." (PMID 40941632, 2025). "Glypican 3 discriminates well between HCC and cholangiocarcinoma (intrahepatic and extrahepatic), since its expression is downregulated in the latter." (PMID 37174934, 2023). "Studies have shown that GPC3's expression rate in non-liver tumors, including mesotheliomas, ovarian tumors, breast tumors, and cholangiocarcinomas, is down-regulated, whereas it is high in HCC." (PMID 27655712, 2016). "Importantly, GPC3 has been reported to discriminate between HCC and non-malignant lesions or other liver-associated cancers like cholangiocarcinoma (CCA)." (PMID 32984308, 2020). "In addition, the expression of GPC-3 protein is often absent in cholangiocarcinoma (CCA)." (PMID 34150644, 2021). "In the same study, GPC3 expression was negative in sarcomatoid HCC, carcinoid tumors, and cholangiocarcinomas." (PMID 27655712, 2016). "IHC revealed uniform expression of CK7 and CK19 but was negative for hepatocyte antigen and Glypican-3 in tumor cells, which argues against the pathological diagnosis of HCC or combined HCC and cholangiocarcinoma." (PMID 27301956, 2016).
neuroblastoma (17 papers, 2004 to 2024). Neuroblastoma (NB) is the most common solid, extracranial childhood tumor. "We selected the SY5Y cell line to further study potential roles of GPC3-Unc5 interactions in neuroblastoma cell migration." (PMID 36240740, 2022). "Neuroblastoma cells express varying levels of GPC3 and Unc5 receptors, with further Unc5 and GPC3 expressed in their environment." (PMID 36240740, 2022). "In our neuroblastoma model, GPC3-Unc5 signaling seems to act as a switch that determines cellular cohesion." (PMID 36240740, 2022). "GPC3 is widely expressed in embryonal tumors and was detected in a subset of aggressive neuroblastoma samples." (PMID 36240740, 2022). "As found for the patient tumor cells, different neuroblastoma cell lines also expressed Unc5 receptors and some GPC3." (PMID 36240740, 2022). "We also show that Unc5/GPC3 signaling is essential for the collective migration of neural-crest derived neuroblastoma cells to their target sympathoadrenal derivatives." (PMID 36240740, 2022). "We analyzed the expression of GPC3 and Unc5 in published single cell RNA-seq data from 16 different neuroblastoma patient samples." (PMID 36240740, 2022). "The results suggest that interfering with the neuroblastoma source of GPC3 disrupts cell migration and targeting to the primary tumor site." (PMID 36240740, 2022). "Controversially, GPC3 gene hyper methylation is observed in adult cancers, which supports argument GPC3 is under expressed in mesothelioma and neuroblastoma." (PMID 33344222, 2020). "There is mixed evidence regarding the role of GPC3 in neuroblastoma, with some studies showing increased expression in patients with 4S disease but most revealing absent expression of GPC3 in nearly all cases." (PMID 30873384, 2019). "The same observations were made with HER2 specific CAR T cells in a xenograft mouse model of HER2low osteosarcoma, with B7-H3 specific CAR T cells in a model of B7-H3low neuroblastoma, and with glypican-3 specific CAR T cells in a model of glypican-3low neuroblastoma." (PMID 38090558, 2023). "Anti-GPC3 nanobodies enhance or weaken Unc5-GPC3 binding and, together with mutant proteins, show that Unc5/GPC3 guide migrating pyramidal neurons in the mouse cortex, and cancer cells in an embryonic xenograft neuroblastoma model." (PMID 36240740, 2022). "The phenotypes observed in cortical migration, together with the widely documented roles of Unc5 and GPC3 in cancer, led us to investigate whether Unc5/GPC3 interaction plays a role in neuroblastoma cell migration." (PMID 36240740, 2022). "The Unc5-GPC3-dependent mechanisms we found in neuroblastoma migration could apply to other disseminating cancers, given that GPC3 is an oncofetal protein expressed by many pediatric solid embryonal tumors and adult cancers." (PMID 36240740, 2022). "We conclude that the GPC3-Unc5 interaction mediates contact-repulsion in these assays and may contribute to cellular navigation in cortical and neuroblastoma cells." (PMID 36240740, 2022).
pancreatic cancer (16 papers, 2017 to 2025). "More importantly, we think that our results suggest that pancreatic cancer in our population is a less promising target for GPC3-targeted immunotherapies than previously thought." (PMID 39598037, 2024). "Their study also found that, in general, the only pancreatic tumor that expresses GPC3 is acinar cell carcinoma." (PMID 39598037, 2024). "Found a 7 gene panel (MDR1, SRBC, VHL, MUC2, RB1, SYK, and GPC3) that detects colorectal and pancreatic cancers with 63.16% sensitivity, 84% specificity, and AUC of 0.8177." (PMID 36980276, 2023). "The results with our protocol for GPC3 immunohistochemistry suggest that pancreatic cancer may be a less promising target for GPC3-targeted immunotherapies than previously thought." (PMID 39598037, 2024). "Given the potential significance of the Yao study for GPC3 as a novel prognostic and predictive marker in pancreatic adenocarcinoma, we wanted to see if we could replicate their GPC3 results in pancreatic cancers in our Canadian patient population." (PMID 39598037, 2024). "GPC1 may ultimately prove to be a more fruitful area for future pancreatic cancer research than GPC3." (PMID 39598037, 2024). "The primary objective of the study was to determine if we could independently identify GPC3 expression in pancreatic cancer in a significant proportion of patients in our Canadian patient population with the antibody protocol we currently use in diagnostic pathology practice." (PMID 39598037, 2024). "The very low rate of GPC3 expression we observed suggests that patients with pancreatic cancer in our population would be unlikely to benefit from novel GPC-targeted therapeutics." (PMID 39598037, 2024).
colorectal cancer (15 papers, 2016 to 2025). A primary or metastatic malignant neoplasm that affects the colon or rectum. "In a study on colorectal cancer, the authors observed a relationship between Notum and GPC3 in which the production of mRNA and protein was inversely correlated." (PMID 38786073, 2024). "Murakami and colleagues identified five CAED patients (0.3%) from 1,666 patients with colorectal carcinomas whose clinical pathological features were analyzed followed by IHC staining with enteroblastic lineage markers: glypican-3 (GPC-3), spalt-like transcription factor 4 (SALL4), and AFP." (PMID 37781207, 2023). "Therefore, the relationship between the expression of GPC3 and the biological behavior of colorectal cancer remains to be further studied." (PMID 34458143, 2021). "The present work was designed to investigate the expression profiling of Glypican-3 (GPC-3) and its association with clinico-pathological features as well as prognostic significance in colorectal carcinoma (CRC)." (PMID 27454254, 2016). "Glypican-3 (GPC3)-targeted and CEA-targeted CAR-T cells have shown modest activity in HCC and colorectal cancer, respectively." (PMID 38550594, 2024). "Currently, glypican-3 (GPC-3) has been tested to modify CAR-T-cells to treat HCC (NCT02715362, NCT03198546, and NCT02905188), as described, as well as for colorectal cancers (NCT02416466, NCT02850536, and NCT00004178)." (PMID 31769427, 2019). "At present, there are not many reports regarding the relationship between GPC3 and the biological behavior of colorectal cancer." (PMID 34458143, 2021).
ovarian clear cell cancer (15 papers, 2014 to 2025). An invasive malignant neoplasm that arises from the ovary and is characterized by a predominance of clear and hobnail malignant epithelial cells. "In a Canadian patient cohort, high membranous GPC3 expression was found in 20% of endometriosis-associated ovarian clear cell carcinomas (OCCCs)." (PMID 36930359, 2023). "Other studies have shown that GPC3 expression was strongly associated with clear cell ovarian carcinomas, and high GPC3-expression was significantly associated with unfavorable outcomes in cases with loss of ARID1A." (PMID 36553184, 2022). "For instance, in HCC cells, clear cell ovarian carcinoma cells, and gastric carcinoma cells, GPC3 has been demonstrated to inhibit tumor growth or metastasis." (PMID 40422229, 2025). "The prognosis of ovarian clear cell carcinoma was poor due to chemoresistance; therefore, immunotherapy, such as the glypican-3 (GPC3) peptide vaccine, gained attraction, as it prolonged survival." (PMID 33535558, 2021).
germ cell tumor (13 papers, 2010 to 2025). A benign or malignant, gonadal or extragonadal neoplasm that originates from germ cells. "Additional negativity for CK20, GATA3, and glypican-3 further excluded metastatic gastrointestinal or germ cell tumors." (PMID 41149460, 2025). "Several studies of extragonadal germ cell tumors demonstrate that yolk sac tumors and choriocarcionomas virtually always express GPC3 via IHC." (PMID 30873384, 2019). "In testicular germ cell tumors, choriocarcinoma was consistently positive for GPC3 with strong staining in the malignant syncytiotrophoblast and weaker staining in the cytotrophoblast." (PMID 20868507, 2010). "Both SALL4 and glypican-3 though considered as marker for germ cell tumor should not be used alone in differentiating MMMT from germ cell tumors." (PMID 22848863, 2012). "These cells in the current case were positive for GPC3 and SALL4, which are known as oncofetal proteins expressed in germ cell tumors, contributing to the need of additional immunohistochemical staining for differentiating germ cell tumors from clear cell type EOC in the current case." (PMID 29933751, 2018). "In our case, germ cell tumors including yolk sac and embryonal carcinoma were the most possible differentials which were excluded by the negative IHC results for SALL4, CD30, Glypican 3 and AFP (alpha-fetoprotein)." (PMID 35797874, 2022). "For example, glypican-3 is often negative in well differentiated HCC, but frequently positive in germ cell tumors." (PMID 33054843, 2020).
glioma (12 papers, 2020 to 2026). A benign or malignant brain and spinal cord tumor that arises from glial cells (astrocytes, oligodendrocytes, ependymal cells). "Notably, neurons adjacent to C420R- and H1047R-mutant gliomas displayed enhanced synaptic imbalance, which was attributed to the secretion of glypican 3 in the case of C420R variant, bridging genetics with peritumoral synaptic remodeling." (PMID 38834748, 2024). "GPC3 from gliomas impairs KCC2 channels in neurons, leading to a paradoxical depolarization response to GABA." (PMID 38193532, 2024). "Glioma-specific mutations in PIK3CA have been implicated in seizure onset, with glypican-3 (GPC3) emerging as a driver of synaptogenesis and hyperexcitation." (PMID 38193532, 2024). "Gpc3-knockout glioma cells with PIK3CA C420R exhibited prolonged survival compared to wild-type Gpc3." (PMID 34944870, 2021). "EGFRvIII and GPC3 are crucial targets in the solcriticalsection in glioma and HCC, respectively." (PMID 36261831, 2022). "Thus, anti-GPC-3 CAR T cells could potentially recognize GPC-3–expressing gliomas and GPC-3 antigens shed in the TME, which poses another target for glioma extracellular matrices that could be useful for dual CAR-targeting strategies." (PMID 34760690, 2021). "Similar to GPC3, some scholars believe that GNAI1 is a tumor-promoting gene and reported up-regulated GNAI1 mRNA in human glioma, which is inconsistent with our data." (PMID 32766727, 2020). "However, considering that GPC3 is a proteoglycan with negatively charged heparan sulfate chains, its hydrophilic water-binding capacity on HCC cell surfaces could reduce water mobility and turn tissue into a more solid-like state, as known for high-grade glioma in the brain." (PMID 36518314, 2022).